SOD3 (superoxide dismutase 3)
Diseases named in the same sentence as SOD3 in open-access papers (continued):
Sharing a sentence is not in itself a finding about the gene and the disease.
allergic disease (2 papers, 2022 to 2023). An immune response that occurs following re-exposure to an innocuous antigen, and that requires the presence of existing antibodies against that antigen. "Taken together, our data showed that SOD3 can be used as an alternative therapy to restrict IgE-mediated allergic diseases." (PMID 35155837, 2022). "Previously, SOD3 has been shown to reduce the serum IgE levels in various allergic diseases." (PMID 35155837, 2022). "Thus, previous studies along with our current findings emphasized the importance of SOD3 as an alternative therapy to restrict IgE-mediated allergic diseases." (PMID 35155837, 2022).
asthma (2 papers, 2020 to 2022). "These interactions of SOD3 in the lung of asthma were altered by the administration of exogenous SOD3." (PMID 32128111, 2020).
bronchopulmonary dysplasia (2 papers, 2018 to 2021). Bronchopulmonary dysplasia is a chronic respiratory disease that results from complications related to lung injury during the treatment of infant acute respiratory distress syndrome in low-birth-weight premature infants or from abnormal lung development in older infants. "Firstly, as it relates to animal models of bronchopulmonary dysplasia, the study was designed to be narrow in scope and assess only the effect of hyperoxia exposure and a single antioxidant enzyme, SOD3." (PMID 34439484, 2021).
coronary stenosis (2 papers, 2016 to 2019). Narrowing of the coronary artery lumen diameter. "Levels of TNF-α, TLR4, ACR, MDA, and hs-CRP were remarkably increased (P < 0.001), and levels of SDF-1α, SOD3, and eNOS were remarkably lowered (P < 0.001) in elderly patients with severe coronary stenosis and multiple coronary chronic total occlusions." (PMID 31780868, 2019).
diabetic cardiomyopathy (2 papers, 2022). Diabetic cardiomyopathy is a disorder of the heart muscle in people with diabetes. "In experimental diabetic cardiomyopathy models, trientine has been demonstrated to increase superoxide dismutase-1 (cytosolic SOD1) and superoxide dismutase-3 (SOD3, also known as extracellular SOD and EC-SOD) expression." (PMID 36145368, 2022).
endometrial cancer (2 papers, 2022 to 2024). Primary or metastatic malignant neoplasm involving the endometrium (mucous membrane that lines the endometrial cavity). "Minimal changes in the overall activity of SOD measured in the serum (SOD1 and SOD3) of the patients with endometriosis and endometrial cancer could be therefore caused by a similar Cu/Zn ratio in these groups as both elements are required for the activation of Cu/Zn SODs." (PMID 37968795, 2024).
endometriosis (2 papers, 2024). The growth of functional endometrial tissue in anatomic sites outside the uterine body. "Our finding of reduced Sod3 expression in decidualized endometrium compared to lesions challenges the narrative linking decreased peritoneal SOD3 activity with endometriosis progression." (PMID 39385609, 2024).
endotoxemia (2 papers, 2020 to 2022). "We know that transgenic mice that overexpress SOD3 have increased resistance to rib cage irradiation with 4-MV photons, to focal cerebral ischemia, to 12-O-tetradecanoylphorbol-13-acetate (TPA) exposure, and to lipopolysaccharide-induced endotoxemia." (PMID 36552527, 2022).
enteritis (2 papers, 2021 to 2025). Inflammation of the small intestine. "Moreover, SOD3 can significantly mitigate enteritis symptoms by preserving the integrity of epithelial junctions and regulating inflammatory and oxidative stress responses." (PMID 40868537, 2025).
glioblastoma (2 papers, 2017 to 2025). The most malignant astrocytic tumor (WHO grade IV). "High levels of oxidative stress-responsive genes, including SOD3 (Superoxide Dismutase 3), correlate with poor prognosis in glioblastoma patients." (PMID 41009025, 2025).
hepatic (2 papers, 2019 to 2024). "High SOD3 activity was expected to effectively neutralize excess O2• − level, however it could result in overproduction of H2O2, which could accumulate and induce hepatic IR." (PMID 31396447, 2019).
infertile (2 papers, 2018 to 2021). "Finally, the SOD3 c.G362A SNP (rs2536512) was recently evaluated in 111 infertile men compared to 104 fertile controls, not detecting an association between genotypes and infertility, although a significant reduction in SOD activity was found in samples from the infertile group." (PMID 33806677, 2021). "It is possible that SOD1 can compensate for the loss of SOD3 in mouse follicles, as mice lacking SOD1 or both SOD1 and SOD3 are subfertile or infertile, respectively (38, –40)." (PMID 29987037, 2018).
inflammatory skin disease (2 papers, 2018 to 2021). Inflammatory skin disorders covers a broad category that includes many conditions ranging in severity, from mild itching to grave medical health complications These disorders are common in people of all ages and races. "The overexpression of superoxide dismutase 3 (SOD3) in MSCs resulted in the increment of cell viability both in vitro and in vivo, contributing to functional improvement of MSCs in various inflammatory skin disease models." (PMID 33806241, 2021). "Thus, SOD3 could be a promising candidate for the treatment of skin inflammatory diseases." (PMID 29507345, 2018).
influenza (2 papers, 2012 to 2023). An acute viral infection of the respiratory tract, occurring in isolated cases, in epidemics, or in pandemics; it is caused by serologically different strains of viruses (influenzaviruses) designated A, B, and C, has a 3-day incubation period, and usually lasts for 3 to 10 days. "Investigating the underlying mechanism using SOD3 transgenic mice will shed light on the in vivo role of SOD3 in inhibiting influenza proliferation." (PMID 36829913, 2023). "Our results further revealed the role of SOD3 in antiviral innate immune responses to influenza virus infection and the role of SOD3 as a novel target for influenza prevention and treatment." (PMID 36829913, 2023). "We then investigated the potential mechanism of SOD3 in influenza pathogenesis and found SOD3 was closely related to the process of viral replication." (PMID 36829913, 2023). "Although SOD3 was reported to minimize influenza-induced lung injury in mice by reducing oxidative stress, the role of SOD3 against pathogen invasion and the mechanisms governing SOD3′s response to influenza virus infection are not well understood." (PMID 36829913, 2023).
keratoconus (2 papers, 2013 to 2019). A degenerative, structural disorder of the eye, characterized by a cone-shaped protrusion of the cornea. "Interleukin-1alpha downregulates SOD3 and the SOD3 reduction leads to insufficient oxidative defense during keratoconus condition." (PMID 30858441, 2019).
kidney damage (2 papers, 2020 to 2022). "In this study, we aimed to elucidate the correlation between different potential predictors (ROS, SOD3, hs-CRP, IL-2, IL-6, and IL-18) and first nephropathy-related hospitalization or death in ESRD patients receiving hemodialysis." (PMID 35740095, 2022).
lung disorder (2 papers, 2018 to 2020). A disease involving the lung. "The relationship between cell ageing and SOD3 gene expression was first characterized in lung disorders with respect to fibroproliferation and excessive deposition of extracellular matrix in late adulthood." (PMID 32887483, 2020).
meningioma (2 papers, 2014 to 2022). A generally slow growing tumor attached to the dura mater. "In this regard, SNPs in the C variant of SOD3 (superoxide dismutase 3), GSTT1 (glutathione S-transferase theta 1), and MUTYH (Muty homolog) have been found to be associated with meningioma risk." (PMID 25003081, 2014).
pancreatic adenocarcinoma (2 papers, 2015 to 2017). "This study emphasizing the relevance of exogenous H2O2 generation by exogenous dismutase activity like that provided by extracellular SOD3 is compatible with other results showing that loss of SOD3 expression promotes an invasive phenotype in human pancreatic adenocarcinoma." (PMID 26356671, 2015).
pancreatic ductal adenocarcinoma (2 papers, 2018 to 2020). An infiltrating adenocarcinoma that arises from the epithelial cells of the pancreas. "It has been known that loss of SOD3 level could contribute to aggressive and refractory nature of pancreatic ductal adenocarcinoma." (PMID 30186549, 2018). "For example, re-expression of SOD3 was reported to diminish the invasiveness and growth of pancreatic ductal adenocarcinoma." (PMID 33330063, 2020).
peritonitis (2 papers, 2009 to 2012). Inflammation of the peritoneum (tissue that lines the abdominal wall and covers most of the organs in the abdomen). "The NOX2 complex independent anti-inflammatory effect of SOD3 was further characterized in peritonitis, and SOD3 was found to reduce macrophage infiltration independently of NOX2 complex functionality." (PMID 22529530, 2012). "SOD3 expression significantly reduced the number of peritoneal infiltrating cells in proteose peptone and IL-1β induced peritonitis in wild type mice." (PMID 22529530, 2012). "The anti-inflammatory properties of SOD3 have been studied in models of pulmonary disease and peritonitis." (PMID 22529530, 2012). "In conclusion, our novel observation shows that SOD3 gene transfer into hind limb ischemia or peritonitis results in significantly reduced leukocyte migration due to decreased cytokine and adhesion molecule expression." (PMID 19495415, 2009). "To confirm the findings and to further analyze the SOD3-derived selective inhibition of cell migration we examined leukocyte migration in a mouse peritonitis model, which provides an efficient way to analyze leukocyte traffic in an acute inflammatory response." (PMID 19495415, 2009). "In the present work we studied leukocyte migration in acute ischemia and peritonitis models and analyzed the contribution of SOD3 on inflammatory cytokine and adhesion molecule expression." (PMID 19495415, 2009). "To compare the efficacy of SOD3 mediated anti-inflammatory effect to existing medication we determined the effect of Dexamethasone in mouse peritonitis." (PMID 19495415, 2009). "Similarly, the degree of SOD3-induced macrophage infiltration inhibition in peritonitis was similar." (PMID 22529530, 2012). "Similarly, pretreating the mice three days before induction of peritonitis allowed us to analyze the effect of SOD3 during substantial SOD3 expression in the peritoneal cavity." (PMID 22529530, 2012). "In the present work the effect of SOD3 on the inflammatory cell extravasation was studied in vivo in rat hind limb ischemia and mouse peritonitis models by identifying the migrated cells and analyzing SOD3-derived response on inflammatory cytokine and adhesion molecule expression." (PMID 19495415, 2009). "We report that SOD3 limits inflammation in CIA and peritonitis both in the presence and in the absence of phagocyte oxidative burst." (PMID 22529530, 2012). "Our results confirm the previously documented anti-inflammatory role of SOD3 and additionally, for the first time, we show that it can downregulate both CIA and peritonitis even in the absence of functional NOX2 complex and phagocyte oxidative burst." (PMID 22529530, 2012).
pneumoconiosis (2 papers, 2018 to 2024). An occupational lung disorder caused by inhalation of dust particles. "The data suggest that SOD3 and extracellular oxidative stress may play an important role in the development of pneumoconiosis and pulmonary vascular remodelling after exposure to environmental and occupational silica." (PMID 38887981, 2024). "Our data suggest that Sod3 and extracellular oxidative stress may play an important role in the development of pneumoconiosis and pulmonary vascular remodeling following exposure to environmental and occupational silica." (PMID 30453980, 2018).
preeclampsia (2 papers, 2023 to 2024). Preeclampsia is a hypertensive disorder of pregnancy that is characterized by new-onset hypertension with proteinuria presenting after 20 weeks of gestation, and depending on mild or severe forms may initially present with severe headache, visual disturbances, and hyperreflexia. "SOD3 is also upregulated in the placenta of preeclampsia patients." (PMID 39480826, 2024).
retinal disease (2 papers, 2021 to 2024). "By isolating the properties of SOD3 and illustrating the effects of its ablation and overexpression, we have presented a viable therapeutic target for retinal diseases complicated by the secondary effects of oxidative stress." (PMID 34679728, 2021).
retinitis pigmentosa (2 papers, 2013 to 2021). Retinitis pigmentosa (RP) is an inherited retinal dystrophy leading to progressive loss of the photoreceptors and retinal pigment epithelium and resulting in blindness usually after several decades. "Patients with retinitis pigmentosa present low total antioxidant capacity including reduced SOD3 activity and protein concentration in aqueous humor." (PMID 24069283, 2013).
Thyroid (2 papers, 2017 to 2019). "Decreased SOD3 is detected in both databases, confirming the earlier observations and suggesting SOD3 as a differentiation marker in thyroid tumorigenesis." (PMID 29478325, 2019).
tuberculosis (2 papers, 2021). A chronic, recurrent infection caused by the bacterium Mycobacterium tuberculosis. "The missense variants SOD3 rs2536512 and rs1799895 and the following variants in non-coding region SOD3 rs699473, rs2855262, and rs8192290, have been analyzed to investigate the possible association with DILI induced by anti-tuberculosis drugs." (PMID 33672092, 2021).
acne vulgaris (1 paper, 2018). "In a mouse model, treatment with SOD3 significantly inhibited P. acnes-induced skin inflammation including ear thickness, erythema, and infiltration of inflammatory cells, suggesting that SOD3 has anti-inflammatory effects in P. acnes-induced acne vulgaris." (PMID 29507345, 2018).
Alzheimer disease (1 paper, 2024). A progressive, neurodegenerative disease characterized by loss of function and death of nerve cells in several areas of the brain leading to loss of cognitive function such as memory and language. "The single herb in GZF, namely Rx Rehmanniae Conquitae (Shu-Dihuang), might possess therapeutic benefits for Alzheimer’s disease by regulating the expression of amy-1, sir-2.1, daf-16, sod-3, and hsp-16.2." (PMID 38921335, 2024).
anaplastic cancer (1 paper, 2021). "Most prominently, SOD3 affected the metabolic processes in the anaplastic cancer model." (PMID 33919252, 2021).
aortic aneurysm (1 paper, 2024). A ruptured aneurysm located in the wall of the proximal portion of the descending aorta proceeding from the arch of the aorta. "SOD3 is under-expressed in aortic aneurysms thus extracellular O2- scavenging is diminished." (PMID 39480826, 2024).
aortic valve calcification (1 paper, 2020). "SOD3 and catalase are downregulated with aortic valve calcification and in CAVS." (PMID 32411328, 2020).
aspergillosis (1 paper, 2024). Aspergillosis is an infection, growth, or allergic response caused by the Aspergillus fungus. "Triple deletion of sod1, sod2, and sod3 genes did not decrease the virulence of A. fumigatus in an immunocompromised murine aspergillosis model; however this triple mutant exhibited increased sensitivity to killing by alveolar macrophages of immunocompetent mice." (PMID 39728319, 2024).
brain tumor (1 paper, 2022). "Among them, the Ala variant of SOD2 rs4880 and the C variant of SOD3 rs699473 are found to be associated with brain tumor risk." (PMID 36307808, 2022). "Thus, the pharmacological or genetic activation of SOD2 and SOD3 could mitigate the risk of brain tumors." (PMID 36307808, 2022). "Single nucleotide polymorphisms of OS-responsive genes, such as CAT, SOD1, SOD2, SOD3, GPx1, NOS3, and PON1 have been found in adult brain tumor studies." (PMID 36307808, 2022).
cardiomyopathy (1 paper, 2021). A disease of the heart muscle or myocardium proper. "Other studies focusing on a Han population found an association between a prognosis of heterogeneous cardiomyopathy with SNPs associated with LGALS3, AGCT, SLC25A13, HRG, APOB, SOD3, SYNM, and TLN2." (PMID 34572079, 2021).
Cognitive impairment (1 paper, 2025). Abnormal cognition is characterized by deficits in thinking, reasoning, or remembering. "By employing adeno-associated viral (AAV) gene therapy to overexpress Sod3 in the ChP, the researchers were able to protect the brain from oxidative damage and prevent cognitive deficits in Methotrexate-treated mice." (PMID 40886025, 2025). "This reduction in Sod3 was associated with increased oxidative stress and cognitive impairment." (PMID 40886025, 2025).
colon cancer (1 paper, 2022). "SOD3 is associated with inhibition of tumour growth and metastasis, while SOD1 and SOD2 are elevated in different stages of several cancers, including colon cancer, and can trigger proliferative and apoptotic signals depending on the amount of H2O2 produced." (PMID 36235125, 2022).
cryptococcal infections (1 paper, 2022). "Moreover, accumulation of lipofuscin, DAF-16 nuclear localization, and expression of superoxide dismutase (SOD-3) were elevated in C. elegans due to host defenses during cryptococcal infections." (PMID 35733100, 2022).
dental caries (1 paper, 2024). The decay of a tooth, in which it becomes softened, discolored, and/or porous. "This study provides new evidence on the impact of genetic polymorphisms in SOD2 and SOD3 genes on the OHRQoL of Para athletes with dental caries experience." (PMID 39109770, 2024). "Polymorphisms in SOD2 and SOD3 are potentially valuable biomarkers of OHRQoL in Para athletes with dental caries experience." (PMID 39109770, 2024). "The positive hypothesis is that polymorphisms of SOD2 and SOD3 genes modulate the impact of OHRQoL in Para athletes with dental caries experience." (PMID 39109770, 2024). "The aim of this study was to evaluate whether polymorphisms in SOD2 and SOD3 genes modulate the oral health-related quality of life (OHRQoL) of Para athletes with dental caries experience." (PMID 39109770, 2024). "Polymorphisms of the SOD2 and SOD3 genes may be important biomarkers of OHRQoL in Para athletes with dental caries experience." (PMID 39109770, 2024). "Thus, this study aimed to evaluate whether polymorphisms of SOD2 and SOD3 genes are associated with OHRQoL in Para athletes with dental caries experience." (PMID 39109770, 2024).
diabetic neuropathy (1 paper, 2022). A chronic, pathological complication associated with diabetes mellitus, where nerve damages are incurred due to diabetic microvascular injury involving small blood vessels that supply these nerves, resulting in peripheral and/or autonomic nerve dysfunction. "In addition, overproduction of metabolites of oxidative stress, such as myeloperoxidase, superoxide dismutase-3, thiobarbituric acid reactive substances (TBARS) and methylglyoxal, were improved to be with progression of diabetic neuropathy." (PMID 35093139, 2022).
Enterococcus faecalis infection (1 paper, 2022). A bacterial infection induced by Enterococcus faecalis which is the most prevalent species (along with Enterococcus faecium) cultured from humans, accounting for more than 90% of clinical isolates. "In C. elegans, activation of DAF-16 has been shown to induce a DAF-16-dependent-superoxide dismutase (SOD)-3 expression during Enterococcus faecalis infections." (PMID 35733100, 2022).
Erythema (1 paper, 2018). Redness of the skin, caused by hyperemia of the capillaries in the lower layers of the skin. "Interestingly, pre- and post-treatment of SOD3 showed significantly less erythema compared with the P. acnes-treated group." (PMID 29507345, 2018).